DGKB (diacylglycerol kinase beta)
Diseases named in the same sentence as DGKB in open-access papers:
DGKB is named in the same sentence as 43 diseases in open-access papers, as found by Europe PMC text mining. Sharing a sentence is not in itself a finding about the gene and the disease. The quoted sentences say what the papers report.
bipolar disorder (5 papers, 2009 to 2020). A disorder of the brain that causes unusual shifts in mood, energy, activity levels and the ability to carry out day-to-day tasks. "Associations with bipolar disorder have been made with DGKβ and DGKη, with lithium treatment resulting in accumulation of DAG in a range of models, independent of phospholipase D." (PMID 30135067, 2018). "Analysis of the human DGKβ gene has demonstrated that a splice variant at the COOH-terminal of DGKβ is related to bipolar disorder." (PMID 22590645, 2012). "Furthermore, it was reported that the splice variant at the COOH-terminal of DGKβ was related to bipolar disorder." (PMID 20976192, 2010). "Recent studies reported that the splice variant at the COOH-terminal of DGKβ was related to bipolar disorder, but its detailed mechanism is still unknown." (PMID 20976192, 2010). "DGKβ KO mice exhibited impaired cognitive functions, including impaired spatial and long-term memories and bipolar disorder-like phenotypes." (PMID 32962151, 2020). "The administration of lithium alleviated the impairment of memory and emotion in the DGKβ KO mice, which suggested that the expression level of DGKβ is a putative biomarker for screening patients with lithium-responsive bipolar disorder." (PMID 32962151, 2020). "In the present study, we performed a comprehensive behavioral analysis of DGKβ KO mice in order to investigate the role of DGKβ in higher brain functions and the relationship between DGKβ and bipolar disorder." (PMID 20976192, 2010). "In terms of pathophysiological implication, it is noteworthy that SV3'DGKβ is annotated in GenBank as being differentially expressed in bipolar disorder patients." (PMID 19691842, 2009). "We made a hypothesis that DGKβ which is suspected of contributing to bipolar disorder, also plays some important roles in ADHD." (PMID 22590645, 2012). "The purpose of our present work was to investigate the involvement of DGKβ in bipolar disorder." (PMID 20976192, 2010). "Of DGKs, mRNA signal for DGKβ is strongly detected in the striatum, and one of the transcripts derived from the human DGKβ locus is annotated in GenBank as being differentially expressed in bipolar disorder patients." (PMID 19691842, 2009). "Analysis of human DGKβ gene reveals the existence of a total of 16 different splice variants, one of which corresponds to an EST annotated in GenBank as differentially expressed in bipolar disorder patients." (PMID 19691842, 2009).
Cognitive impairment (5 papers, 2010 to 2020). Abnormal cognition is characterized by deficits in thinking, reasoning, or remembering. "In DGKβ knockout (KO) mice, cognitive impairment, mania-like behavior, and increased seizure susceptibility were observed." (PMID 33139624, 2020). "Previously, we demonstrated that DGKβ knockout (KO) mice showed various dysfunctions of higher brain function, such as cognitive impairment (with lower spine density), hyperactivity, reduced anxiety, and careless behavior." (PMID 22590645, 2012). "Taken together, DGKβ KO mice present lithium-sensitive excitatory psychomotor effects related to their mood state and cognitive impairment." (PMID 20976192, 2010). "Studies have shown that DGKβ knockout mice exhibit cognitive impairment and anxiety." (PMID 32824857, 2020). "DGKβ is closely related to formation of neurite spine, and DGKβ-knockout mice demonstrated behavioral disturbances, such as emotional, attentional, and cognitive impairment that may be attributed, at least in part, to the impairment of cortical spine formation." (PMID 32751985, 2020).
Anxiety (4 papers, 2010 to 2020). Intense feelings of nervousness, tension, or panic often arise in response to interpersonal stresses. "DGKβ KO mice exhibited some behavioral abnormalities, such as hyperactivity, reduced anxiety, and reduced depression." (PMID 20976192, 2010). "On the other hand, the number of entries into and the time spent in open arms of DGKβ KO mice were greater than vehicle-treated WT group, and at the same or larger levels than anti-anxiety drug-treated WT mice." (PMID 20976192, 2010). "In an elevated plus maze test, DGKβ KO mice displayed enhanced open arm selectivity, which also indicates lowered anxiety of DGKβ KO mice." (PMID 20976192, 2010). "To further assess anxiety levels of DGKβ KO mice, we conducted another anxiety measuring behavioral test, an elevated plus maze test." (PMID 20976192, 2010). "In open field test, we also assessed the anxiety level of DGKβ KO mice by measuring their stay time in the center area of open field apparatus (anxiety-provoking area for mice)." (PMID 20976192, 2010). "In the open field test, DGKβ KO mice spent more time in the center of the apparatus than WT mice, indicating that DGKβ KO mice showed less-anxiety." (PMID 20976192, 2010). "Based on these results, DGKB could be a good candidate locus for traits that affect changes in synaptic formation and are involved in locomotion and anxiety-related behavioral patterns." (PMID 33139624, 2020).
neuroblastoma (3 papers, 2010 to 2021). Neuroblastoma (NB) is the most common solid, extracranial childhood tumor. "To elucidate the mechanisms involved in neuronal development by DGKβ, we investigated the importance of DGKβ activity in the induction of neurite outgrowth using human neuroblastoma SH-SY5Y cells." (PMID 34944458, 2021).
Obesity (3 papers, 2013 to 2024). Accumulation of substantial excess body fat. "DGKB has also been shown to interact directly with induced obesity and abnormal lipid metabolism proteins, which play an important role in the pathogenesis of metabolic syndrome and age-related diseases resulting from dyslipidemia." (PMID 39459569, 2024).
schizophrenia (3 papers, 2010 to 2022). A major psychotic disorder characterized by abnormalities in the perception or expression of reality. "As we can see from above, both DGKB and PCMTD2 are closely related to the brain and have the possibility to be associated with schizophrenia." (PMID 36186431, 2022). "As outlined in S11 Table, seven of these genes have, to varying degrees, plausible links to cognition (i.e. DGKB, NPS, VPS13B, RBM20, ABHD4, ESRRB, and DOPEY2), with some active in systems implicated in schizophrenia pathology (NPS, DGKB, ABHD4, ESRRB)." (PMID 25860228, 2015).
type 2 diabetes (3 papers, 2010 to 2018). "DGKB, the diacylglycerol kinase βgene, which regulates the intracellular concentration of the second messenger diacylglycerol, was also recently associated with fasting glucose and type 2 diabetes risk." (PMID 29777116, 2018). "Additionally, rs2191349 in DGKB, rs1799884 and rs4607517 in GCK, and rs11558471 in SLC30A8 were nominally associated with IFG and type 2 diabetes (p = 0.011, 0.027, 0.045, and 0.002, respectively) after adjusting for age, sex, and BMI." (PMID 29777116, 2018). "Of these loci, only GCK, MTNR1B, DGKB, GCKR, ADCY5 and PROX1 (besides TCF7L2 and SLC30A8) were associated with type 2 diabetes at genome-wide significance levels, with several others (but not all) showing a consistent trend but not meeting the same stringent statistical threshold." (PMID 22984506, 2012). "Besides, the effects of previous reported type 2 diabetes and/or fasting glucose loci G6PC2, GCK, GCKR, MTNR1B, DGKB, SLC30A8 and TCF7L2 were also replicated in the meta-analysis." (PMID 21103350, 2010).
colorectal cancer (2 papers, 2020 to 2023). A primary or metastatic malignant neoplasm that affects the colon or rectum. "In a multi‐omics study of colorectal cancer, Tuzzerel was also the microbiol genus that was most associated with other genes and metabolites, including a negative association with serum uric acid levels and the expression of BEST4 and DGKB genes." (PMID 38107095, 2023). "The genes in the reported colorectal cancer group include POLR1D, DGKB, SULT2B1 SMPD1 GOT2, MTHFD1L and ACADM." (PMID 32285560, 2020).
depression (2 papers, 2010 to 2023). "Our genome-wide analysis identified DGKB rs12666606 as a pleiotropic variant between endometriosis and depression." (PMID 36652249, 2023). "Only DGKB (OMIM 604070) rs12666606 pleiotropy between endometriosis and depression survived genome-wide multiple testing correction (z scores, −9.46 for endometriosis and 8.10 for depression; r = 12.45; θ P = 5.56 × 10−8, θ q = 4.95 × 10−4) (eTable 8 in Supplement 1)." (PMID 36652249, 2023).
Diabetes (2 papers, 2012 to 2023). "We examined the association between CDKAL1 rs10946398, GCK rs1799884, GCKR rs780094 and DGKB/TMEM195 rs2191349 gene polymorphisms and the development of post-transplant diabetes in kidney transplant patients treated with tacrolimus." (PMID 37628646, 2023). "The lack of evidence on the association of polymorphisms of other analysed genes involved in glycaemic regulation (GCK, GCKR, DGKB/AGMO) with the risk of post-transplant diabetes in kidney transplant recipients suggests that they do not play a key role in the development of this type of diabetes." (PMID 37628646, 2023). "The aim of this study was to evaluate the association of selected polymorphisms of genes affecting carbohydrate metabolism, such as CDKAL1 rs10946398, GCK rs1799884, GCKR rs780094 and DGKB/TMEM195 rs2191349, with the development of post-transplant diabetes in kidney transplant patients." (PMID 37628646, 2023).
melanoma (2 papers, 2019 to 2022). A malignant, usually aggressive tumor composed of atypical, neoplastic melanocytes. "Diacylglycerol kinase (DGKB), TGc domain-containing protein (Tgm2), structural maintenance of chromosomes 4 (SMC4) and mastermind-like transcriptional coactivator 2 (MAML2) were related to lipid metabolism, facilitating melanoma development in the severe-EMN group." (PMID 35202347, 2022).
mood disorder (2 papers, 2010 to 2014). A cognitive disorder a disturbance in which the person's mood is hypothesized to be the main underlying feature. "The mouse model for mood disorders generally exhibits changes in their depressive states, i.e. model mouse of mania exhibits lower depressive states; we evaluated these changes in DGKβ KO mice using forced swim test and tail suspension test." (PMID 20976192, 2010).
asthma (1 paper, 2021). "The association of NOSIP and DGKB with biomarker levels of the workers in our study provides novel evidence that NOS and nitric oxide may be impacting the toxicokinetics of isocyanates even before asthma development." (PMID 34335698, 2021).
attention deficit-hyperactivity disorder (1 paper, 2012). A disorder characterized by a marked pattern of inattention and/or hyperactivity-impulsivity that is inconsistent with developmental level and clearly interferes with functioning in at least two settings (e.g. at home and at school). "In the present study, we conducted further tests on DGKβ KO mice in order to investigate the function of DGKβ in the central nervous system, especially in the pathophysiology of attention deficit hyperactivity disorder (ADHD)." (PMID 22590645, 2012).
breast carcinoma (1 paper, 2017). "It is notable that among obese women, 50% of cancer risk was mediated via glucose metabolism trait, owing to two SNPs: in breast cancer, in relation to GCKR through glucose, and in CRC, in relation to DGKB/TMEM195 through HOMA-IR." (PMID 28446149, 2017).
cognitive decline (1 paper, 2015). "In humans, DGKB has been associated with stimulating the secretion of insulin, a hormone found to have potent effects in the brain, with insulin dysfunction underlying several risk factors implicated in cognitive decline." (PMID 25860228, 2015).
dementia (1 paper, 2024). Loss of intellectual abilities interfering with an individual's social and occupational functions.
epilepsy (1 paper, 2018). A brain disorder characterized by episodes of abnormally increased neuronal discharge resulting in transient episodes of sensory or motor neurological dysfunction, or psychic dysfunction. "It is also interesting to note that previous studies have shown a reduction in dendritic spines in epilepsy patients, that DGKβ controls dendritic spine outgrowth and maturation, and that VPA treatment increases dendritic spine formation in mouse models." (PMID 30135067, 2018).
glioblastoma (1 paper, 2020). The most malignant astrocytic tumor (WHO grade IV). "For example, DGKζ binds directly to Rac1 to form a complex with Rho-GDI and PAK1, DGKβ co-localized with actin filaments, whereas endogenous DGKζ co-purified with cytoskeletal proteins and localized to the leading edge of C2 myoblasts and glioblastoma cells." (PMID 32722576, 2020).
glioma (1 paper, 2021). A benign or malignant brain and spinal cord tumor that arises from glial cells (astrocytes, oligodendrocytes, ependymal cells). "Additionally, ETV1 is likely to be methylated in CIC wild-type, IDH-mutated, 1p/19q-codeleted gliomas, and fused with DGKB in pediatric high‐grade gliomas, acting as an oncogenic driver." (PMID 33470396, 2021).
Insulin resistance (1 paper, 2025). Increased resistance towards insulin, that is, diminished effectiveness of insulin in reducing blood glucose levels. "A genetic study showed that DGKB involved loci associated with insulin secretion and processing, potentially leading to insulin resistance, and further connected to T2D." (PMID 41393296, 2025).
memory impairment (1 paper, 2010). "Therefore, the relationship between hyperactivity and memory impairment in DGKβ KO mice is weak." (PMID 20976192, 2010).
metabolic syndrome (1 paper, 2024). A cluster of metabolic risk factors for CARDIOVASCULAR DISEASES and TYPE 2 DIABETES MELLITUS. "We found DGKB is directly correlated with these proteins and may lead to metabolic syndrome resulting from abnormal lipid metabolism." (PMID 39459569, 2024).
myocardial infarction (1 paper, 2021). Gross necrosis of the myocardium, as a result of interruption of the blood supply to the area, as in coronary thrombosis. "In genome-wide association studies, these genes have been identified in connection with myocardial infarction (DGKB); immune function, rheumatoid arthritis, and sarcoidosis (BTNL2); and bone mass in different ethnic groups (TGFBR3)." (PMID 34201265, 2021).
osteoporosis (1 paper, 2021). A condition of reduced bone mass, with decreased cortical thickness and a decrease in the number and size of the trabeculae of cancellous bone (but normal chemical composition), resulting in increased fracture incidence. "These three SNPs belong to the genes DGKB, BTNL2, and TGFBR3 that were indicated in previous genome wide association studies with CVD (DGKB), rheumatoid arthritis and sarcoidosis (BTNL2), and bone mass and osteoporosis (TGFBR3), respectively." (PMID 34201265, 2021).
rectum adenocarcinoma (1 paper, 2022). An adenocarcinoma arising from the rectum. "Finally, we predicted and verified 8 GRSDMs in adrenocortical carcinoma (ACC), rectum adenocarcinoma (READ), uveal Melanoma (UVM), thyroid carcinoma (THCA), and predicted 4 GRSDMs (F2RL3, DGKB, GRK5, PIK3R6) which were sensitive to 12 potential drugs." (PMID 35885996, 2022).
Stroke (1 paper, 2021). Sudden impairment of blood flow to a part of the brain due to occlusion or rupture of an artery to the brain. "The circRNAs originating from the DGKB gene (circ_Dgkb_13, circ_Dgkb_14, and circ_Dgkb_10) collectively target SOX9 via miR-124-3p, thus affecting axonal budding after stroke." (PMID 34868302, 2021).
cancer (7 papers, 2014 to 2026). A tumor composed of atypical neoplastic, often pleomorphic cells that invade other tissues. "In two examples of mutations in Cyclin-dependent kinase 2 (CDK2) and Diacylglycerol kinase, beta (DGKB) genes, we show how the in vivo assay reveals novel insights on the functions of these genes in cancer." (PMID 25260652, 2014). "Four proteins identified in the faecal proteome are potential biomarkers of the cancer, including diacylglycerol kinase (DGKB, DGK), mastermind-like transcriptional coactivator 2 (MAML2), structural maintenance of chromosomes 4 (SMC4), IG domain-containing protein and transglutaminase 2 (Tgm2)." (PMID 35202347, 2022). "For example, gene DGKB of UVM in TCGA is specifically high, and gene DGKB was also specifically high in the GEO data set or the testing dataset; DNA methylation levels of gene F2RL3 was significant higher in ACC than other cancer types in the training, testing and GEO validation sets." (PMID 35885996, 2022). "Yet, data on the role of GSTM5, PDE6B, SGPP2, PDE1B, DGKB, and PLCG2 in cancer are still lacking." (PMID 33282950, 2020).
neurological diseases (2 papers, 2012 to 2025). "Further studies on the functions of DGKβ may lead to clarification of the mechanisms of many neurological diseases." (PMID 22590645, 2012).
tumor (2 papers, 2022 to 2025). "A total of 120 (27.9%) tumor samples harbored mutations in glycerolipid metabolism-related genes, with two genes identified as high frequently mutated, including DGKB (15%) and DGKD (14%)." (PMID 35600382, 2022). "Compared to adjacent normal tissues, tumor tissues exhibited significantly reduced expression of PTGIS, DGKB, HSD17B13, INMT, and ACACB, while PLA2G10, GRHL1, LIPG, and PLA2G4F were markedly upregulated." (PMID 40426878, 2025).
DGKB also shares sentences with these, for which no sentence is quoted: Cirrhosis (1 paper); coronary artery disease (1); endometriosis (1); Ewing sarcoma (1); kidney transplant (1); lung carcinoma (1); mucosal (1); prediabetes (1); prostate carcinoma (1); rheumatoid arthritis (1); sarcoidosis (1); thyroid carcinoma (1); uveal melanoma (1).